FGF2 (fibroblast growth factor 2)
Diseases named in the same sentence as FGF2 in open-access papers (continued):
Sharing a sentence is not in itself a finding about the gene and the disease.
tumor (continued). "For tumor angiogenesis, FGF-2 seems to collaborate with the VEGF-VEGFR2 signaling to ensure both processes of endothelial cell proliferation and sprouting simultaneously occur." (PMID 32709869, 2020). "FGF2 was correlated with tumor size (p = 0.026), gender (p = 0.047), and lymph metastasis (p = 0.007) in ESCC tissues." (PMID 33381388, 2020). "After the tumor spheroids were established, we treated the tumor spheroids with FGF2 or FGF2-SPIONs (equivalent to 250 ng/ml FGF2) and standard chemotherapy gemcitabine (3 μg/ml) every 3 day." (PMID 31911892, 2020). "In contrast, their monotherapy had no impact on tumor cell proliferation in FGF-2+ tumors, although anti-VEGF and imatinib monotherapy significantly inhibited tumor cell proliferation in FGF-2− tumors." (PMID 32709869, 2020). "The increased activity of FGF-2/FGFR autocrine/paracrine loops in malignancies is also considered as a potent mechanism of tumor resistance to conventional therapies, including targeted therapies." (PMID 32599808, 2020). "In fact, FGF-2 contributes to tumor progression not only by inducing neovascularization but also by modulating growth, differentiation, migration, and survival in a variety of cancer cell types." (PMID 32456056, 2020). "To corroborate the xenograft data, we examined FGF-2 expression in tumor specimens obtained from treatment-naive GIST patients (n = 20), and patients received IM-based therapy for at least 12–16 months (n = 10)." (PMID 32599808, 2020). "In parallel a reduction of the tumor microenvironment in response to the treatment-induced tumor shrinkage will reduce the paracrine secretion of FGF2." (PMID 32344828, 2020). "Fibroblast growth factor 2 (FGF2) is a well-defined YAP/TAZ target expressed in both tumor cells and ECs." (PMID 33614496, 2020). "The FGF2 pathway is being considered as an important angiogenic pathway involved in bypassing tumor resistance to anti-angiogenic therapies that target VEGF signaling." (PMID 33614496, 2020). "These independent findings validate the fact that anti-VEGF and imatinib combination therapy is highly effective in suppressing FGF-2+ tumor growth and angiogenesis, which would be otherwise resistant to their monotherapy." (PMID 32709869, 2020). "Quantitative ELISA assay of tumor tissue samples showed that FGF-2 expressional level was 392 ng g−1 tissue." (PMID 32709869, 2020). "FGF2 is induced in the tumour microenvironment following fractionated radiation in murine tumours consistent with clinical reports." (PMID 32792542, 2020). "ASCs migrate toward chemo-residual TNBC cells via SDF-1α/CXCR4 signaling, and drive chemo-residual tumor cell proliferation in a paracrine manner by secreting FGF2 and activating ERK." (PMID 30594967, 2019). "As for other growth factors, pro‐tumor roles have been attributed to FGF2 signaling in different models and contexts." (PMID 30422399, 2019). "In the current study, we provide novel evidence regarding the role of GPER in the regulation of FGF2 expression triggered by estrogens within the tumor microenvironment." (PMID 30866584, 2019). "Significantly, tumor cells have been reported to actively manipulate the binding capacity of their HSPGs for FGF-2 and other growth factors, by modifying the overall density and sulfation pattern of their HSPGs." (PMID 32010611, 2019). "Here, we studied the roles of FGF2 during the regulation of TGF‐β‐induced mesenchymal transition of tumor endothelial cells (TECs)." (PMID 31094056, 2019). "The HT-29 cell line showed very low levels of both FGF-2 isoforms in the 2D and micro-tumor cell models." (PMID 31248208, 2019). "Fibroblast growth factor-2 (FGF-2; or basic fibroblast growth factor) has been implied in different biological processes, such as limb and nervous system development, wound healing, and tumor growth, due to its function in cell proliferation and survival." (PMID 31035689, 2019).
tumor (continued). "Vascular endothelial growth factor (VEGF) and fibroblast growth factor-2 FGF2 are among the factors that play an important role in tumor angiogenesis." (PMID 31402861, 2019). "The fact that other protocols omit FGF2 in their culture media but use, depending on tumour’s stage, other activators of different pathways instead, indicates that self-renewal can be activated via additional pathways which have many interconnections." (PMID 31758153, 2019). "In ovarian cancer, mutual cross-talk between tumor cells and umbilical vein endothelial cells (UVECs) activates AKT-associated signals in both cell types, thereby inducing the secretion of FGF-2 by HUVECs." (PMID 30927928, 2019). "HSulf-1 suppresses FGF-2-mediated tumor cell proliferation and invasion, HSulf-2 augments these activities to progress disease, as examined in HCC." (PMID 32010611, 2019). "In eight cases that showed PROX1 downregulation in the tumor tissue, the FGF2 expression fold change was higher than PROX1." (PMID 31717665, 2019). "Our work shows that ASC-driven proliferation of chemo-residual tumor cells is dependent on their secretion of FGF2." (PMID 30594967, 2019). "The secretion of PF4 and TSP1 leading to displacement of VEGF and FGF2 from HS binding sites is an important mechanism of tumor angiogenesis regulation." (PMID 31379588, 2019). "While BET inhibitors are shown to be efficacious in vitro by inducing apoptosis and cell cycle arrest, we show evidence that FGF2 in the TME reduces the responses of tumor cells to BET inhibitor growth inhibitory effects." (PMID 30610113, 2019). "Reduction of tumor volume and weight, suppression of angiogenesis partly via FGF2/FGFR2 signaling pathway." (PMID 31402861, 2019). "When this effect is stronger than the sequestration that occurs when PF4 binds directly to pro-angiogenic factors, the level of unbound VEGF and FGF2 will be higher compared to the tumor microenvironmental condition with lower PF4 secretion (Column I)." (PMID 31379588, 2019). "Knock-down of EIF4E results in suppression of the tumorigenic and angiogenic properties of the FaDu cell line manifested by loss of capacity to grow in soft agar, reduced expression of angiogenic factors (FGF-2 and VGF), and loss of tumor growth in nude mice." (PMID 31010087, 2019). "FGF2 neutralizing antibody reduced the ability of ASC CM to drive proliferation of SUM159 chemo-residual SUM159 tumor cells by 1.6-fold." (PMID 30594967, 2019). "Once within the tumor microenvironment, these ASCs secrete a factor (FGF2) that acts in a paracrine fashion on chemo-residual TNBC cells to induce their proliferation." (PMID 30594967, 2019). "We thus assessed the impact of free Tris DBA-Pd and Tris DBA-Pd nanoparticles on FGF2 expression within tumor xenografts using immunohistochemistry (IHC)." (PMID 30824801, 2019). "As a response, tumour cells interact with CAFs by secreting growth factors (such as FGF-2 and PDGF) and chemokines (such as CXCL12) as well as inducing mechanical stress that eventually leads to CAF activation." (PMID 30944831, 2019). "Vascular endothelial growth factor (VEGF) and fibroblast growth factor-2 (FGF2) are among the factors that play an important role in tumour angiogenesis." (PMID 31877856, 2019). "In PCa, elevated autocrine fibroblast growth factor 2 (FGF-2) promotes tumor cell growth by stimulating DNA synthesis, ERK1/2, AKT and FRS-2α (fibroblast growth factor receptor substrate-2)." (PMID 29732010, 2018). "Taken together, these data demonstrate that FGF-2-stimulated pericytes significantly remodel tumor vasculatures and vascular functions." (PMID 29423271, 2018). "This study identifies Cep57 as a haploinsufficient tumor suppressor with biologically diverse roles in centrosome maturation and Fgf2-mediated bone formation." (PMID 30035751, 2018).
tumor (continued). "In FGF-2+ tumors, tumor microvessels were highly perfused with 2000-kD Rhodamine-labeled lysinated dextran, which were significantly compromised in the Fgf2-shRNA-transfected tumors." (PMID 29423271, 2018). "FGF-2 is a known potent growth factor that stimulates tumor angiogenesis and angiogenic endothelial cells." (PMID 29423271, 2018). "Growth of tumor vessels depends not only on VEGF but also on various types of other angiogenic factors such as FGF-2 and angiopoietin-1." (PMID 30279483, 2018). "In active MM plasma cells secrete VEGF and FGF-2 that induce the cells of the tumor microenvironment to secrete their own VEGF, FGF-2, and HGF, able to recruit and activate the MM-associated macrophages." (PMID 30002349, 2018). "Fgf2-shRNA significantly inhibited tumor growth and tumor angiogenesis relative to the control scrambled-shRNA-transfected tumors." (PMID 29423271, 2018). "Similar to 3T3 fibroblast-originated tumors, FGF-2 was able to stimulate tumor growth and angiogenesis compared to those of vector-control tumors." (PMID 29423271, 2018). "So far, the tumor suppressor function of miR‐15/16, which targets important drivers of malignant growth such as FGF2 and the anti‐apoptotic protein Bcl‐2, has been well established in various tumor types including prostate, lung, ovarian, and MPM." (PMID 29094504, 2018). "FGF/FGFR regulates normal and tumour cells growth, differentiation and angiogenesis, and the complex interaction and crosstalk between tumour angiogenic factors, such as FGF2 and PDGFR, promoted tumour growth and metastasis." (PMID 29527128, 2018). "Again, genetic knockdown of FGF-2 by Fgf2- shRNA markedly increased vascular permeability of tumor vessels." (PMID 29423271, 2018). "By directly and indirectly targeting different steps of perivascular cell proliferation and migration, FGF-2 effectively recruits perivascular cells onto the tumor vasculature." (PMID 29423271, 2018). "Similar results were obtained in a zebrafish/tumor xenograft model where the angiogenic response to FGF2-overexpressing tumor cells was strongly impaired by the co-injection of PTX3 or ARPCA." (PMID 30349543, 2018). "When exposed in vitro to VEGF and FGF-2, tumor macrophages differentiated into cells similar to MM endothelial cells, able to generate in vitro capillary-like networks." (PMID 30002349, 2018). "Measurement of leakiness of 70-kD Rhodamine-labeled lysinated dextran showed that FGF-2 protected tumor microvasculatures from leakiness, consisting with the known functional property of pericytes in prevention of vascular leakage." (PMID 29423271, 2018). "Since, FGF-2 is a potent cell survival factor involved in tumor angiogenesis we decided to evaluate FGF-2 expression in EL4, K12, and MDA-MB-231 cells." (PMID 30564299, 2018). "To define FGF receptors (FGFRs) in mediating FGF-2-induced pericyte recruitment in tumor vasculatures, we isolated fresh pericytes from tumor tissues and immediately checked receptor expression." (PMID 29423271, 2018). "In this context, the dramatic increase in fibronectin content, which was consistent with the specific maximal expression in FGF2 of this tumor, suggests that fibronectin plays an essential role as a critical mechanoregulator of the ECM." (PMID 29662647, 2018). "As the PDGF–PDGFR system is the best-characterized signaling pathway in pericyte recruitment in angiogenic vessels, we investigated the effects of PDGFRα and PDGFRβ specific blockades in pericyte recruitment in FGF2+ tumor models." (PMID 29423271, 2018). "It is well known that the mainly fraction of the FGF-2 produced by the tumor cells is secreted and remain bind to the heparan sulfate proteoglycans in the cytoplasmic membrane." (PMID 30564299, 2018). "Except E-Cadherin and FGF-2, all other markers tested were expressed highly in tumor tissues as compared to periphery of tumors." (PMID 30333909, 2018).
tumor (continued). "Collectively, these results demonstrate that Cep57T is a partially functional allele, and that Cep57 is a multifunctional protein with important roles in centrosome maturation, tumor suppression, and Fgf2-mediated skeletal development." (PMID 30035751, 2018). "FGF2, HGF and EGF are associated with the angiogenesis, growth, proliferation and differentiation of numerous cell types, including certain tumor cells." (PMID 28486560, 2017). "Consistent with this possibility, α3(V)-free ECM from KO/PyMT tumour cells and ECM of WT/PyMT tumour cells in which GPC1 had been knocked down both contained less FGF2 than did control WT/PyMT tumour cell ECM." (PMID 28102194, 2017). "Recombinant IGF-1 increased tumor cell expression of FGFR-3 as did co-cultured TAB cells, and reciprocally, recombinant FGF-2 induced IGF-1 production in NB cells as did co-cultured tumor cells." (PMID 28928360, 2017). "miR-15/16 promotes tumor angiogenesis and metastasis by enhancing the expression of FGF2, and miR-503 inhibits tumor angiogenesis and growth by simultaneously downregulating FGF2 expression." (PMID 29163456, 2017). "A comprehensive analysis revealed that host cell-derived FGF2 was up-regulated in the bevacizumab-resistant tumor, suggesting that FGF2 played an important role in the acquired resistance." (PMID 29286323, 2017). "This is particularly evident in the context of cancer with FGF2 being a major mediator of tumor-induced angiogenesis." (PMID 28722655, 2017). "FGF2, a known angiogenic factor, was highly upregulated (z-score = 9.86) in our patient's tumor, making it an important target." (PMID 28993730, 2017). "We demonstrated that ECs promote proliferation of tumor cells through releasing a combination of selective angiogenic factors, such as FGF2, IGF-1, IL-8, IL-6, and SDF1." (PMID 26762853, 2016). "These tumor-associated leukocytes drive tumor growth by releasing growth factors, such as epidermal growth factor (EGF), vascular endothelial growth factor (VEGF) and fibroblast growth factor 2 (FGF2)." (PMID 27589805, 2016). "Previous work demonstrated that FGFR1 genomic amplification and increased FGF2 mRNA levels correlated with response to GSK3052230 in tumor xenograft models." (PMID 27223434, 2016). "FGF2 is one member of fibroblast growth factor family, which had a close relationship to tumor development." (PMID 26901069, 2016). "When these cells were exposed for 24 hours to a hypoxia-inducing treatment (100 μM CoCl2) as a tumor-relevant stressor and then treated with Bay60-6583 for another 24 hours, the expression of both FGF2 and CXCL12 increased." (PMID 27590504, 2016). "In spite of a few contradictory finding, FGF2 is considered a significant tumor biomarker and a potential therapeutic target." (PMID 27007053, 2016). "Activated fibroblasts also produce proteases, such as MMPs that degrade ECM and promote secretion of growth factors including FGF2 in the tumor microenvironment." (PMID 27007053, 2016). "It has been reported that various molecules can inhibit FGF2 (ligand) activity, binding, or expression in endothelial and tumor cells." (PMID 27007053, 2016). "This belief originated from experiments in which forced expression of a SULF in several tumor lines caused reduced growth-factor signaling by HB-EGF, FGF-2 or HGF, and diminished tumorigenicity." (PMID 26882224, 2016). "FGF2 exerts its effects on endothelial cells via a paracrine mode after being released by tumor and stromal cells or through mobilization from ECM." (PMID 27007053, 2016). "The correlation between the expression of SOX2 in the primary tumor and lymph node metastasization fits well with its ability to upregulate critical tumor promoting factors such as FGF2, VEGF-C and NRP2." (PMID 26540632, 2016). "msFGFR2c significantly inhibited cell proliferation, induced apoptosis, suppressed tumor growth and angiogenesis in cancer cells overexpressing FGF-2 and c subtype of FGFRs in vitro and in vivo." (PMID 28049184, 2016).
tumor (continued). "FGF2 contributes to tumor progression through enhanced expression and/or release from tumor, endothelial, or stromal cells as well as release from local reservoirs in the ECM." (PMID 27007053, 2016). "Significant correlations between serum FGF2 levels and tumor stage, size, and metastasis were reported in endometrial, colorectal, esophageal, head and neck, liver, renal, and testicular cancers." (PMID 27007053, 2016). "PTTG1, an oncogene, is involved in tumor progression, growth, proliferation, and metastasis by regulating several growth factors, such as fibroblast growth factor 2 and vascular endothelial growth factor." (PMID 26900962, 2016). "Many problems exist with VEGF inhibition therapy such as acquired resistance, due to the tumour microenvironment switching to utilise other pro-angiogenic growth factors such as fibroblast growth factor-2 (FGF2)." (PMID 26620208, 2016). "Tumor sections of mice treated with PSB1115 also showed reduced expression of basic fibroblast growth factor (FGF)-2." (PMID 27590504, 2016). "The dodecasaccharide reduced the number of phospho-FRS2-positive blood vessels by 47%, showing that [NSIS6S]-[NSIS]5 is an effective inhibitor of FGF2-mediated tumor angiogenesis." (PMID 27490176, 2016). "Endogenously synthesized fibrinogen interacts with several growth factors (including VEGF and FGF-2), which promotes cellular adhesion, proliferation and migration of tumor cells and neoplastic angiogenesis." (PMID 26930207, 2016). "A more recent version of this FGF trap was specifically engineered to have high binding affinity with FGF2 and was administered as a recombinant protein; this showed an anti-tumour effect in two different xenograft models." (PMID 26620208, 2016). "This selective translation is mediated by the overexpression of eIF4E-BPs and eIF4G and is particularly advantageous for cancer cells as VEGF, FGF-2, HIF1α, and Bcl-2 are all significant factors in promoting tumor growth and survival." (PMID 28083147, 2016). "VE-cadherin gene expression has been shown to be upregulated in tumour angiogenesis and is upregulated in response to FGF2." (PMID 26620208, 2016). "We found that FGF2 expression was significantly increased in ccRCC tissues relative to the matched non-tumor tissues (P < 0.05)." (PMID 25890121, 2015). "Given the capacity of ARPCA to act as a FGF2/FGF8b-trap (and present work), we assessed its therapeutic potential also in this steroid-regulated tumor model driven by the autocrine/paracrine action of both FGFs." (PMID 25912421, 2015). "Here, we demonstrate that CDV inhibits metastasis induced by FGF2-driven, virus-independent tumor cells." (PMID 25609197, 2015). "CCK-8 assay, migration assay and invasion assay revealed that over-expression of FGF2 significantly reversed the tumor suppressive effects of miR-203 on 786-O cell (P < 0.05)." (PMID 25890121, 2015). "The secretion of growth factors, such as vascular endothelial growth factor (VEGF) and FGF2, by irradiated tumor cells can protect endothelial cells from apoptosis induced by ionizing radiation." (PMID 25794049, 2015). "Taken together, these findings indicated that restoration of FGF2 markedly attenuated the tumor suppressive effect of miR-203." (PMID 25890121, 2015). "Accordingly, ARPCA exerts a significant inhibitory on the growth and vascularization of TRAMP-C2 tumor grafts, a classical model of steroid hormone-dependent prostate cancer characterized by FGF2/FGF8b co-expression." (PMID 25912421, 2015). "Unlike VEGF, FGF2 selectively binds its receptor FGFR2 and stimulates angiogenesis, tumor growth and endothelial cell migration, indicating that FGF2 has biological activity in vivo." (PMID 26575424, 2015). "Meanwhile, emerging evidence suggests that FGF2 functions as a potential oncogenic protein driving a variety of tumor malignancies." (PMID 26056081, 2015).